BDNF (brain derived neurotrophic factor)
Diseases named in the same sentence as BDNF in open-access papers (continued):
Sharing a sentence is not in itself a finding about the gene and the disease.
depression (continued). "Decreased BDNF is associated with age-related hippocampal dysfunction, memory impairment, and an increased risk of depression, and exercise prevents aging-induced cognitive dysfunction by activating the hippocampal PGC-1α/FNDC5/BDNF pathway." (PMID 35805170, 2022). "The possible mechanism is to increase activation of astrocytes in the hippocampus through the Pg-LPS/TLR4 signaling pathway, leading to downregulating astrocyte p75NTR and inhibiting BDNF maturation and, ultimately, depression." (PMID 36440396, 2022). "Accumulating evidence shows that neuroplastic mechanisms dependent of BDNF are deleteriously changed in major depression and animal models of depressive disorder." (PMID 35069013, 2022). "Studies have shown that decreased BDNF accompanies conditions such as depression, bipolar disorder, and schizophrenia." (PMID 36294343, 2022). "It contributed to neuroprotection against chronic unpredictable mild stress by enhancing brain-derived neurotrophic factor expression and improving hippocampal neurogenesis in a rat model of depression." (PMID 36003380, 2022). "Rat hippocampus were used to determine the levels of BDNF and other neurotransmitters associated with CUMS-induced depression-like behavior." (PMID 35237160, 2022). "BDNF is a growth factor crucial in brain plasticity, learning and memory functions, and is abnormally reduced in patients suffering from depression." (PMID 36078738, 2022). "A recently published clinical study has reported significantly lower BDNF plasma concentrations in schizophrenic patients with concomitant depression." (PMID 35269761, 2022). "Although aging has received much attention recently, age-dependent expression of BDNF-TrkB and the mechanisms involved in depression require further investigation." (PMID 36430921, 2022). "We extended the analysis to BDNF and mGlu2 receptor expression in the frontal cortex and hippocampus, which are key regions in the pathophysiology of depression." (PMID 35721218, 2022). "Majority of the studies conducted so far, to establish the correlation between depression and DNA methylation of BDNF, revealed hypermethylation of BDNF gene in depressed patients compared to healthy individuals." (PMID 36583185, 2022). "BDNF-TrkB system not only plays a key role in depression and in normalizing the stress response, but also appears to be an important factor in the functioning of astrocytes." (PMID 35563389, 2022). "Peripheral BDNF levels have been shown to increase after antidepressant treatment in patients with major depressive disorder and after mindfulness-based interventions in different study populations." (PMID 35250657, 2022). "RORA, a transcription factor that downregulates BDNF, was targeted by hsa-miR-181c-5p and hsa-miR-20a-5p that were correlated with depression and education, respectively." (PMID 36040555, 2022). "Clinical studies in major depressive disorder patients have shown that BDNF and TrkB levels were downregulated in the hippocampus and frontal cortex." (PMID 35462923, 2022). "The inadequacy of pharmacokinetic profiles, such as poor parenteral bioavailability and possible promotion of multiple myeloma progression, also limits the use of peripheral BDNF in treating depression." (PMID 36499240, 2022). "BDNF plays a major role in the pathophysiology of depression and the treatment of antidepressants mainly by binding to its TrkB receptor." (PMID 35875795, 2022). "The deletion of brain-derived neurotrophic factor (BDNF) and upregulation of indoleamine 2,3-dioxygenase 1 (IDO1) are associated with depression severity in animals." (PMID 35711916, 2022).
depression (continued). "In a mouse model, a single-nucleotide polymorphism in the brain-derived neurotrophic factor (BDNF) gene induces anxiety-like and depression-like behavior in response to estradiol administration, similarly to what occurs in women with PMDD83." (PMID 35574174, 2022). "Ginsenoside Rb1, for example, has been shown to have potential antidepressant-like effects in depression model mice by increasing BDNF signaling and encouraging hippocampus neurogenesis." (PMID 36249818, 2022). "Several studies have shown that antidepressants increase the level of BDNF in plasma and improve the symptoms of depression." (PMID 36061856, 2022). "Butyric acid can also increase the concentration of the central neurotransmitter 5-HT, promote the expression of brain-derived neurotrophic factor (BDNF), and significantly improve depression-like behavior in CUMS model mice." (PMID 35312878, 2022). "A previous study reported that exercise alleviates depression-like behavior in chronically stressed rats by increasing BDNF in the striatum." (PMID 35814204, 2022). "We also aimed to investigate the differences in BDNF, proBDNF, and S100B levels between depression in the course of bipolar disorder (BD) and major depressive disorder (MDD)." (PMID 35448545, 2022). "This depression-like phenotype is associated with an increment in BDNF signaling, but not DA transmission, in the VTA and Acb shell of mice and an increase in BDNF protein and mRNA expression in the PFC of rats." (PMID 36499323, 2022). "Reduced blood levels of BDNF have been reported in major depression (MD), and depressed mood is a frequent co-morbidity in FMS." (PMID 35455956, 2022). "Relevant experiments have confirmed that the BDNF content in the plasma of patients with depression and other mental diseases is decreased, and the comorbidity rate of depression and ED is high." (PMID 36661494, 2022). "In the present study, plasma BDNF levels did not correlate with BMI, whereas an evident relationship with BDI-II emerged, overall suggesting the strong impact of BDNF on depression." (PMID 35911513, 2022). "In this study, 5300 publications on the role of BDNF in depression and treatment were evaluated by bibliometrics as of 2 August 2022, so as to further clarify the research hotspots and trends in the association between depression and BDNF." (PMID 36291673, 2022). "The protein and mRNA expressions of FXR in hippocampus were significantly increased in CUMS induced depressive rats, and FXR overexpression aggravated depression-like behaviors by inhibiting brain-derived neurotrophic factor signaling in the hippocampus." (PMID 35321330, 2022). "Physical activity increases the concentration of several neurotrophic factors, including BDNF, thus possibly exerting a protective effect against depression." (PMID 35996095, 2022). "In patients with major depressive disorder, elevated BDNF was related to increased NREM quality and SWA." (PMID 36294343, 2022). "Six meta-analyses found decreased BDNF levels in BD patients compared with both healthy individuals and patients with unipolar depression." (PMID 35163764, 2022). "On the other hand, the strong clinical link between pain and depression adds more complexity to the relationship between BDNF and FM nociplastic pain." (PMID 35501732, 2022). "Surprisingly, duloxetine decreased serum BDNF level significantly in the FM patients even after adjusting for the disease severity, depression, and pain level." (PMID 35501732, 2022). "Notable downregulated genes matching depression were: BDNF, the glucocorticoid receptor, NR3C1, and activity related genes, EGR1, FOS, NR4A1, FOSB, and ARC." (PMID 34997033, 2022). "Hippocampal neurogenesis was determined by Nissl staining, while 5-hydroxytryptamine (5-HT), tryptophan/kynurenine ratio, and brain-derived neurotrophic factor (BDNF) in the hippocampus were analyzed as biochemical indicators of depression." (PMID 35814253, 2022).
depression (continued). "In patients with depression, exercise was found to induce significant increases in serum levels of BDNF levels in all assessed participants." (PMID 35887357, 2022). "It proposes the role of telomere length together with BDNF as an intermediary between loneliness and depression." (PMID 36497531, 2022). "Anxiety and depression behaviors were assessed by open field tests (OFT) and forced swimming tests (FST), while interleukin 18 (IL-18), 5-hydroxytryptamine (5-HT) and brain-derived neurotrophic factor (BDNF) were the molecular biomarkers of depression." (PMID 36422003, 2022). "In this study, the serum BDNF levels were negatively correlated with the HAMD-24 scores in patients with reactive depression, suggesting that the BDNF levels can reflect the severity of depression in patients with reactive depression." (PMID 35295780, 2022). "Decreased BDNF mRNA and/or protein levels are related to many nervous system diseases such as Alzheimer disease, depression and autism." (PMID 35893846, 2022). "For instance, in the case of depression with lower levels of BDNF, the first line treatment should be those antidepressants that are shown to raise BDNF levels, such as agomelatine." (PMID 35370811, 2022). "Here we have reviewed research relevant for the role of hypothalamic BDNF signaling in depression-related symptomology." (PMID 36466807, 2022). "Depression-linked histone methylation modifications in astrocytes also have been detected for genes involved in the signaling of trophic factors such as BDNF, which is altered in some subjects with depression and in stress models." (PMID 35530179, 2022). "Total BDNF (tBDNF) and mBDNF levels were measured in 23 patients with severe treatment-resistant depression before (baseline) they received a course of ECT." (PMID 35203890, 2022). "Research involving animal models of depression have demonstrated that BDNF serum levels are reduced, and that this is correlated with the duration of the condition, albeit not symptom severity in MDD." (PMID 35887357, 2022). "For instance, creatinine or microalbumin in nephropathy, neurofilament light (Nfl), amyloid-beta-42/tau proteins in cognition, brain derived neurotropic factor (BDNF) in depression, and B-type natriuretic peptide (BNP) in cardiomyopathy." (PMID 35682911, 2022). "Consistently, in an experimental model of depression in rodents, Mg exerted anti-depressant activity through the BDNF pathway." (PMID 36613667, 2022). "Subsequent clinical studies assessing BDNF levels in patients with depression have identified an important correlation between depression and BDNF levels, finding that increased BDNF levels are a key indicator of antidepressant effectiveness." (PMID 36186850, 2022). "Isolated mitochondria significantly reduced hippocampal astrocyte and microglia activation and neuroinflammation (i.e., 1L-1β, TNF-α, and COX-2), increased BDNF expression, and restored ATP production dysfunction and oxidative stress in LPS-induced depression." (PMID 36440427, 2022). "Altered circulating BDNF levels are known to be related to metabolic and neuropsychiatric disorders including dementia, depression, stroke, diabetes, CVD, and osteoporosis." (PMID 36329115, 2022). "Multiple meta-analyses have demonstrated that BDNF is significantly lower in most individuals with untreated depression compared to healthy controls." (PMID 35295780, 2022). "Here, we identify CREB/BDNF as one of the critical molecules that participate in the development of neuropathic pain and depression, and found that the mechanism of central sensitization resembles the ACC and spinal." (PMID 35401106, 2022). "This is consistent with the observation that increased EphA4 signaling in the mPFC modulates brain-derived neurotrophic factor (BDNF) signaling in the social defeat mouse model of depression." (PMID 35271507, 2022).
depression (continued). "The occurrence of depression is related to low serum BDNF levels in the hippocampus and prefrontal cortex, and its pathophysiological mechanism is mainly the damage of neuroplasticity." (PMID 36506019, 2022). "The administration of BDNF in midbrain regions or the hippocampus diminished depression-like behaviors and mimicked the effects of antidepressants." (PMID 36430254, 2022). "Synaptic plasticity is essential for the physiological morphology of neurons, and BDNF is one of the crucial regulators in this process making it a therapeutic target in depression." (PMID 36014336, 2022). "Reduction of BDNF levels affects formation of synaptic spine density, and decreases excitatory neurons leading to depression." (PMID 35911513, 2022). "Oxytocin signaling plays a role in the pathophysiology of depression, schizophrenia, anxiety, and cognition, and interestingly, these same conditions are found to display lower levels of BDNF." (PMID 35721318, 2022). "Our results led to the conclusion that BDNF cannot be used as reliable clinical biomarker for depression." (PMID 35510613, 2022). "As BDNF plays a major role in protecting the brain from depression, many researchers and scientists have investigated other signaling pathways that can modulate BDNF expression." (PMID 36499295, 2022). "Decreased BDNF is another significant factor in the pathogenesis of depression (Castrén and Rantamäki, 2010)." (PMID 36686689, 2022). "EVs play a vital role in the pathogenesis of depression by transporting miRNA and effector molecules such as BDNF, IL34." (PMID 35401216, 2022). "Using a linear mixed model, we showed that duloxetine reduced serum BDNF level significantly, even after adjusting for depression, pain and severity of the disease (p value< 0.01)." (PMID 35501732, 2022). "In pathological states, serum BDNF levels decrease, such as in patients with Alzheimer’s disease, schizophrenia, and depression." (PMID 35998179, 2022). "The BDNF-TrkB system not only plays a key role in depression and in normalizing the stress response, but also appears to be an important factor in the functioning of astrocytes." (PMID 35563389, 2022). "Research on the behavior of diabetes combined with depression revealed that eplerenone reduces neuroinflammation, promotes the maturation of brain-derived neurotrophic factor (BDNF), and exerts neuroprotective and antidepressant effects." (PMID 36325528, 2022). "The research showed that playing Go can improve the quality of life of patients by reducing depression and the severity of AD by increasing the concentration of BDNF." (PMID 36142042, 2022). "On the other hand, it is well established that BDNF plays a role in the effects of both monoaminergic and fast-acting antidepressants, like ketamine, on synaptic plasticity, neuronal structure, and depression-like behavior." (PMID 36499323, 2022). "This study evaluated the anti-depressant effect of minocycline on alcohol abstinence-induced depression models in mice and found that minocycline in higher dose (50 mg/kg) showed antidepressant effect and lowered BDNF levels, showing restored neurogenesis." (PMID 36211101, 2022). "Hippocampal biopsies showed that individuals with major depression reveal lower levels of BDNF and its receptor TrkB, and long-term use of antidepressants promotes increased BDNF levels." (PMID 36761172, 2022).
depression (continued). "Luteolin-7-O-glucuronide reduces depression via BDNF activation; however, further studies are needed on the gut–brain axis or the microbial community of the GIT." (PMID 36499295, 2022). "BDNF levels were significantly reduced in the brain and serum of patients with anxiety and depression." (PMID 35634463, 2022). "The fight against depression can be undertaken by either exploring the mechanism for boosting BDNF production or by identifying new potential antidepressant agents that can either substitute for BDNF or increase BDNF levels in the brain." (PMID 36499295, 2022). "In animal studies, butyrate was shown to accelerate BDNF expression in the hippocampus via inhibition of histone deacetylase, and to improve depressive behavior in stress-induced depression model mice." (PMID 35163104, 2022). "The “neurotrophic theory” posits that neurons will lose access to trophic factors as the expression level of BDNF decreases, leading to neuronal atrophy, decreased synaptic plasticity, and the onset of depression." (PMID 36408279, 2022). "Here, CORT induced depression-like behavior, although this effect was limited to BDNF het-Met mice when testing grooming latency and the number of grooming sessions compared to their controls treated with vehicle." (PMID 34848858, 2022). "An impairment of BDNF signaling is involved in the pathophysiology of depression, and mechanisms of BDNF-dependent neuronal plasticity have been consistently implicated in the response to antidepressant medication (reviewed by Castrén and Monteggia, 2021)." (PMID 35721218, 2022). "Patients with decreased function in the prefrontal cortex, hippocampus, and other depression-related structures also have decreased brain-derived neurotrophic factor expression." (PMID 36038574, 2022). "Studies have shown that MMP-9 participates in anxiety- and depression-like behaviors in mouse hippocampus in a BDNF-dependent manner." (PMID 35634463, 2022). "Many investigations have been conducted on the value of blood BDNF as a biomarker of dementia, depression, and stroke." (PMID 36329115, 2022). "Some researchers believed Met/Met subgroup was more sensitive to stress, and BDNF Met-early life stress interaction predicted elevated neuroticism, higher depression and anxiety levels in PD patients." (PMID 35815047, 2022). "Triterpenoids are the most active compounds of Poria cocos, and their intervention significantly improved depression-like behavior in CUMS rats and restored the BDNF levels and neural growth in the hippocampus, which was impaired by depression." (PMID 36499295, 2022). "As the most widely distributed and widely studied neurotrophic factor in the mammalian brain, BDNF is also highly correlated with depression, and is therefore often investigated in the studies of depression." (PMID 36291673, 2022). "Naringenin alleviates depression by regulating oxidative stress and the expression of nuclear factor-κB (NF-κB) and brain-derived neurotrophic factor and by modulating HPA axis dysfunction." (PMID 36506595, 2022). "Low plasma levels of BDNF have previously been reported in patients suffering from neuropsychiatric diseases such as bipolar disease, schizophrenia, and depression." (PMID 36078878, 2022). "Mature brain-derived neurotrophic factor (BDNF) serum levels were significantly lower in patients with major depressive disorders than those in healthy individuals." (PMID 35370878, 2022). "Both clinical and preclinical research have implicated a critical role for brain-derived neurotrophic factor (BDNF) signaling in depression pathology as well as therapeutics." (PMID 36466807, 2022). "Single-nucleotide polymorphic (SNP) variants of BDNF, such as rs6265 (Val66Met), increase the binding ability of the 5-HT1A receptor, a potential endophenotype of depression." (PMID 36075922, 2022).